DLGAP5 (DLG associated protein 5)
Description:
Potential cell cycle regulator that may play a role in carcinogenesis of cancer cells. Mitotic phosphoprotein regulated by the ubiquitin-proteasome pathway. Key regulator of adherens junction integrity and differentiation that may be involved in CDH1-mediated adhesion and signaling in epithelial cells.
Synonyms: HURP; DLG7; KIAA0008; DLG1
Tractability: Small molecule: a structure with a bound ligand is known. PROTAC: UniProt records ubiquitination sites on it; ubiquitination databases record sites on it.
Gene: Protein-coding gene on chromosome 14 (55,148,110 to 55,191,608, reverse strand). Ensembl gene ENSG00000126787.
Subcellular location: Nucleus; Cytoplasm; Cytoplasm, cytoskeleton, spindle
Subcellular location (Human Protein Atlas): Cytosol; Mitotic spindle
Pathways (Reactome):
Signal Transduction: NOTCH3 Intracellular Domain Regulates Transcription
Gene Ontology:
Molecular function: protein binding; microtubule binding
Biological process: centrosome localization; chromosome segregation; kinetochore assembly; mitotic chromosome movement towards spindle pole; mitotic spindle organization; positive regulation of mitotic metaphase/anaphase transition; regulation of mitotic cell cycle; signaling
Cellular component: cytosol; mitotic spindle; nucleus; spindle pole centrosome; cytoplasm; spindle
Genetic constraint (gnomAD): Loss-of-function variants: 73 observed, 79.78 expected, observed/expected ratio (o/e) 0.92, 90% interval 0.76 to 1.11. The upper end of that interval is the gene's LOEUF score, 1.11, which puts it in group 4 of 6, group 1 being the genes least tolerant of losing a copy. Missense variants: 874 observed, 858.28 expected, observed/expected ratio (o/e) 1.02, 90% interval 0.96 to 1.08. Synonymous variants: 273 observed, 286.58 expected, observed/expected ratio (o/e) 0.95, 90% interval 0.86 to 1.05.
Homologues: Orthologues: chimpanzee DLGAP5 (98% identical), macaque DLGAP5 (93% identical), dog DLGAP5 (76% identical), rabbit DLGAP5 (73% identical), pig DLGAP5 (73% identical), guinea pig DLGAP5 (58% identical), mouse Dlgap5 (58% identical), rat Dlgap5 (55% identical), tropical clawed frog dlgap5 (32% identical), zebrafish dlgap5 (26% identical), Drosophila melanogaster mars (17% identical). Paralogues in human: DLGAP2 (17% identical), DLGAP3 (16% identical), DLGAP1 (16% identical), DLGAP4 (16% identical).
Diseases named in the same sentence as DLGAP5 in open-access papers:
DLGAP5 is named in the same sentence as 70 diseases in open-access papers, as found by Europe PMC text mining. Sharing a sentence is not in itself a finding about the gene and the disease. The quoted sentences say what the papers report.
hepatocellular carcinoma (24 papers, 2009 to 2025). A malignant tumor that arises from hepatocytes. "DLGAP5 was associated with an increase in immune‐related pathways, such as T cell receptor pathway and B cell receptor pathway, This confirms the importance of these genes for hepatocellular cancer." (PMID 39910622, 2025). "Discs large‐associated protein 5 (DLGAP5), also known as hepatoma upregulated protein (HURP), has been initially found to be upregulated in hepatocellular carcinoma cells." (PMID 40416599, 2025). "DLGAP5 has been identified as being upregulated across various cancer types, including hepatocellular carcinoma, bladder cell carcinoma, and migratory cell carcinoma." (PMID 39100078, 2024). "Increased DLGAP5 expression contributed to the resistance of prostate cancer and hepatocellular carcinoma cells to γ-radiation and cisplatin, respectively." (PMID 36712920, 2023). "DLGAP5 knockdown resulted in dramatically reduced proliferative and invasive potential in colorectal, clear cell renal cell carcinoma, and hepatocellular carcinoma." (PMID 36712920, 2023). "Strikingly, elevated DLGAP5 expression suppressed apoptosis in prostate cancer and hepatocellular carcinoma cells induced by γ-radiation and cisplatin, respectively." (PMID 36712920, 2023). "They, therefore, guess that DLGAP5 regulates the M phase progression of hepatocellular carcinoma cells." (PMID 33956061, 2021). "Meanwhile, other studies also identified that DLGAP5 was detected in various cancers, including hepatocellular carcinoma and ovarian cancer cells, suggesting its potential role as a fetal oncoprotein." (PMID 30513573, 2018). "DLGAP5, more often referred to as HURP (Hepatoma Up-Regulated Protein), plays critical roles in the tumorigenesis or resistance to therapy of several malignancies, such as hepatocellular carcinoma, lung cancer and prostate cancer." (PMID 30386706, 2018). "Specifically, the knockdown of DLGAP5 not only significantly inhibited the proliferation and invasion of colorectal, clear cell renal cell carcinoma, hepatocellular carcinoma, and pancreatic cancer cells but also induced cell cycle arrest in ovarian and breast cancer cells." (PMID 36712920, 2023). "Additionally, cBioPortal web was utilized to analyze the genetic alteration of DLGAP5, after which we selected hepatocellular carcinoma (HCC) cell lines to define the function of DLGAP5." (PMID 34454476, 2021). "We have observed that DLGAP5 promotes the proliferation and invasion of hepatocellular carcinoma (HCC) cell lines." (PMID 34454476, 2021). "Under the condition of high expression of DLGAP5, the sensitivity of Hepatocellular carcinoma (HCC) cells to apoptosis induced by cisplatin and paclitaxel decreased." (PMID 33312770, 2020). "Moreover, DLGAP5 promotes the proliferation and invasion of hepatocellular carcinoma (HCC), bladder cancer (BLCA), and breast cancer." (PMID 39902297, 2024). "The same tumor, hepatocellular carcinoma, was promoted for recurrence also by the action of ECT2 and, along with NEK2 and DLGAP5, ECT2 was identified via a genome-scale analysis to act as a prognostic biomarker in lung cancer." (PMID 37106813, 2023).
lung carcinoma (19 papers, 2017 to 2024). "DLGAP5 has been reported as an underlying prognostic factor in lung cancer, BC, clear cell renal cell carcinoma, and colorectal cancer and the overexpression of DLGAP5 has been proved to be linked to poor prognosis in these cancers." (PMID 37958803, 2023). "DLGAP5 has been identified as a significant diagnostic and prognostic biomarker in human lung cancer, and silencing DLGAP5 can considerably inhibit the proliferation and invasion of liver cancer cells." (PMID 32782440, 2020). "DLGAP5 promotes lung cancer cell proliferation through regulation of the cell cycle and is associated with multiple immune infiltrating cells." (PMID 36712920, 2023). "Collectively, these data strongly demonstrated that DLGAP5 promotes the proliferation of lung cancer cells by regulating the cell cycle." (PMID 36712920, 2023). "DLGAP5 mRNA and protein abundance were significantly elevated in LUAD, and knockdown of DLGAP5 remarkably suppressed lung cancer cell proliferation through induction of cell cycle G1 arrest." (PMID 36712920, 2023). "Previous articles determined that DLGAP5 overexpression had also been shown in lung cancer, breast cancer, pancreatic cancer, endometrial cancer, and colorectal cancer." (PMID 35873473, 2022). "In lung cancer, DLGAP5 overexpression was found to correlate with decreased OS and relapse-free survival." (PMID 35204661, 2022). "The present study identified and validated NUF2, KIF4A, KIF18B, DLGAP5, NEK2, and LRRK2 as promising diagnostic biomarkers for lung cancer." (PMID 36499051, 2022). "Many studies have been conducted to focus on the multifunctional DLGAP5 protein and have reported functional correspondence between DLGAP5 and tumorigenesis of liver cancer, pancreatic cancer, lung cancer, and ovarian cancer." (PMID 34454476, 2021). "Further, the pooling analysis results of the Oncomine database verified that compared to normal controls, the expression of DLGAP5 was significantly higher in colorectal cancer, sarcoma cancer, breast cancer and lung cancer (all P < 0.05) tissues." (PMID 34454476, 2021). "Subsequently, ROC analysis was performed to assess the diagnostic value of NEK2, DLGAP5 and ECT2 as biomarkers detecting lung cancer." (PMID 28808310, 2017). "A recent genome-scale analysis found that DLGAP5 were highly expressed in lung cancer samples, and presented the ability to diagnose lung cancer and predict the prognosis, suggesting a vital role in the occurrence and development of lung cancer." (PMID 38414025, 2024). "There is evidence that DLGAP5 contributes to tumorigenesis and progression of numerous cancer types, for example, bladder cancer, endometrial cancer, ovarian cancer and lung cancer." (PMID 38414025, 2024). "Furthermore, DLGAP5 knockdown significantly inhibited the proliferation and colony formation of lung cancer cells." (PMID 36712920, 2023). "The knockdown of DLGAP5 resulted in cell cycle G1 arrest in lung cancer cells A549 and H1975." (PMID 36712920, 2023). "DLGAP5 has been found significantly over-expressed in different subtypes of lung cancer, and it could be a promising prognostic biomarker and therapeutic target, which are consistent with the results of this study." (PMID 32411535, 2020). "In addition, the receiver operating characteristic (ROC) analysis and evaluation showed that DLGAP5 expression in patients with lung cancer and normal controls was significantly different." (PMID 32782440, 2020). "Another potential predictor of lung cancer diagnosis and prognosis is DLGAP5." (PMID 28808310, 2017). "Furthermore, in order to assess the prognostic value of NEK2, DLGAP5 and ECT2 as biomarkers for lung cancer, we investigated the association between the expression levels of each of these targets with survival through Kaplan-Meier analysis." (PMID 28808310, 2017). "Furthermore, we further verified whether the abnormally elevated DLGAP5 expression was related to the proliferation of lung cancer cells." (PMID 36712920, 2023).
lung carcinoma (continued). "However, the detailed mechanism by which DLGAP5 leads to poor clinical prognosis in lung cancer remains unknown." (PMID 35204661, 2022). "Although PBK, RRM2, and DLGAP5 are also significant in cancer biology, EXO1’s potential impact on lung cancer mechanisms and treatment is particularly noteworthy." (PMID 39777332, 2024). "DLGAP5 was highly expressed in LUAD tissues and promoted the proliferation of lung cancer cells through regulation of cell cycle." (PMID 36712920, 2023). "For the first time, we propose NUF2, KIF4A, KIF18B, DLGAP5, NEK2, and LRRK2 as biomarkers for lung cancer progression." (PMID 36499051, 2022). "As well, we found that DLGAP5 higher expressed cases was related to poorer OS (P < 0.001), FP (First progression) (P < 0.001), and PPS (P = 0.039) prognosis in lung cancer." (PMID 34454476, 2021). "The increased expression of NEK2, DLGAP5 and ECT2 in lung cancer was identified in three GEO datasets." (PMID 28808310, 2017). "The Cox proportional hazards regression model was also used to evaluate the predictive value of NEK2, DLGAP5 and ECT2 mRNA levels in lung cancer patients." (PMID 28808310, 2017). "The expression levels of NEK2, DLGAP5 and ECT2 were significantly higher in lung cancer patients than in normal subjects." (PMID 28808310, 2017). "Four genes (C1QTNF6, DLGAP5, HMMR, and PLEK2) were identified as key genes in LUAD progression, which were upregulated in the cancerous tissue compared with in the normal tissue (P < 0.001), and correlated with an unwanted prognosis in lung cancer (P < 0.05)." (PMID 37910672, 2023). "Similarly, DLGAP5 expression was significantly related with OS (P = 0.001) and RFS (P = 0.003) of lung cancer patients." (PMID 28808310, 2017). "In this study, we identified and validated the expression of NEK2, DLGAP5 and ECT2 in multiple lung cancer datasets, and the results showed that the expression levels of these three genes were significantly higher in lung cancer patients than in normal subjects." (PMID 28808310, 2017). "ROC analyses showed that NEK2, DLGAP5 and ECT2 levels could also robustly distinguish lung cancer patients from normal subjects, demonstrating high AUC, specificity and sensitivity values." (PMID 28808310, 2017). "Collectively, our results suggest that NEK2, DLGAP5 and ECT2 could be suitable biomarkers for lung cancer diagnosis." (PMID 28808310, 2017). "Taken together, our findings revealed that NEK2, DLGAP5 and ECT2 might be used as promising biomarkers for the early detection of lung cancer, as well as predicting the prognosis of lung cancer patients." (PMID 28808310, 2017). "Taken together, these findings indicate that NEK2, DLGAP5 and ECT2 overexpression might be used as promising biomarkers for the diagnosis and prognosis of lung cancer." (PMID 28808310, 2017). "Similarly, ROC analyses showed that DLGAP5 and ECT2 levels could also robustly distinguish lung cancer patients from normal subjects, demonstrating high AUC, specificity and sensitivity values." (PMID 28808310, 2017). "The expression levels of NEK2, DLGAP5 and ECT2 were similar to those in our training cohort, with significant differences in expression between tumor and normal, suggesting that the differential expression statuses of these three genes is a common feature of lung cancer." (PMID 28808310, 2017). "Furthermore, we performed receiver operating characteristics (ROC) analysis to assess the diagnostic value of these lung cancer biomarkers, and the results suggested that NEK2, DLGAP5 and ECT2 expression levels could robustly distinguish lung cancer patients from normal subjects." (PMID 28808310, 2017).
breast carcinoma (16 papers, 2015 to 2025). "Research by Yujie Li has shown that DLGAP5 regulates breast cancer cell proliferation, migration, invasion, and the cell cycle via the JAK2/STAT3 signaling axis." (PMID 40406126, 2025). "Past research revealed that DLGAP5 is mainly related to various types of cancers, including breast cancer, bladder cancer, gastric cancer, etc 41-43." (PMID 40959279, 2025). "For instance, DLGAP5 expression was upregulated in various cancers and related to poor prognosis, including endometrial, glioma, bladder, and breast cancers." (PMID 36712920, 2023). "For instance, downregulation of DLGAP5 expression suppressed the proliferation and induced cell cycle arrest of ovarian and breast cancer cells." (PMID 36712920, 2023). "Nucleolar and Spindle Associated Protein1 (NUSAP1) inhibits the proliferation of invasive breast cancer cells by regulating DLGAP5 expression." (PMID 34298705, 2021). "The total protein of DLGAP5 obtained from the CPTAC datasets revealed elevated expression of DLGAP5 in the tissues derived from breast cancer, ovarian cancer, UCEC and LUAD (P < 0.001) than that in normal tissues." (PMID 34454476, 2021). "These functional analyses agree on the association of a few genes with breast cancer survival and prognosis, such as DLGAP5, NCAPG, and RRM2, which are not involved in 1CM." (PMID 39125744, 2024). "Next, with the aid of Kaplan–Meier plotter tool, we performed survival data analysis, finding that higher expression DLGAP5 was connected with poorer OS (P < 0.001), DMFS (Distant metastasis-free survival) (P < 0.001) and RFS (Relapse-free survival) (P < 0.001) prognosis in breast cancer." (PMID 34454476, 2021).
lung adenocarcinoma (12 papers, 2013 to 2026). A carcinoma that arises from the lung and is characterized by the presence of malignant glandular epithelial cells. "To explore the impact of DLGAP5 mutations in LUAD patients, we examined DLGAP5 mutation rates using five lung adenocarcinoma cohorts." (PMID 36712920, 2023). "Our study demonstrated that DLGAP5 expression was significantly different between low- and high-grade histologic types of lung adenocarcinoma." (PMID 35204661, 2022). "DLGAP5 is DLG associated protein 5, thought to play multiple roles in carcinogenesis and has been established as a promising early detection biomarker for lung adenocarcinoma and bladder cancer." (PMID 33160365, 2020). "Through clustering of a genome-scale co-expression network, lung adenocarcinoma modules were revealed; in few modules, the genes such as DLGAP5 and BIRC5 are present that play a crucial role in cell cycle progression." (PMID 28808310, 2017). "After intersection with The Cancer Genome Atlas–Lung Adenocarcinoma prognostic genes, three genes, exonuclease 1 (EXO1), family with sequence similarity 83, member A (FAM83A), and disks large-associated protein 5 (DLGAP5), were identified as prognostic gene signatures." (PMID 35204661, 2022). "In addition, there are some genes in other modules that can have very important roles in lung adenocarcinoma, namely DLGAP5, BIRC5, PSMD2, Src, TTK, SENP2, PSMD2, DOK2, FUS among others." (PMID 23874428, 2013). "Furthermore, DLGAP5 predicts poor prognosis and response to immunotherapy in lung adenocarcinoma." (PMID 36712920, 2023). "Immunohistochemistry (IHC) demonstrated that mRNAs DLGAP5, MCM7, RACGAP1, and RRM2 were upregulated in lung adenocarcinoma (LUAD)." (PMID 32149133, 2020). "Moreover, DLGAP5 knockdown significantly inhibited cell proliferation and PLK1 expression in lung adenocarcinoma." (PMID 39624268, 2024).
ovarian carcinoma (12 papers, 2013 to 2024). A malignant neoplasm originating from the surface ovarian epithelium. "Similarly, higher DLGAP5 expression level was also associated with poorer OS (P = 0.007) for ovarian cancer." (PMID 34454476, 2021). "MicroRNA-409-5p inhibits cell proliferation and induces G2/M phase arrest and apoptosis by targeting DLGAP5 in ovarian cancer cells." (PMID 37958803, 2023). "Thus, DLGAP5 knockdown could attenuate cell growth and induce apoptosis via cyclin-dependent kinase 1/cyclin D1/Bcl-2 signaling in ovarian cancer cells." (PMID 36499051, 2022). "DLGAP5 is also a direct downstream target of NOTCH3, which partially explains the mechanism of how NOTCH3 activation promotes ovarian cancer from the perspective of mitotic aberrations." (PMID 32782440, 2020).
bladder cancer (11 papers, 2020 to 2025). "DLGAP5 represents a potential target for therapeutic intervention aimed at mitigating chemoresistance in bladder cancer BLCA." (PMID 39990228, 2025). "Recent studies have elucidated two pivotal mechanisms of DLGAP5 in bladder cancer." (PMID 41153357, 2025). "Interestingly, the detection of DLGAP5 mRNA in urine was a valuable noninvasive test for early diagnosis of bladder cancer and bloodstream bladder cancer, which improved the sensitivity of urine cytology by up to 91%." (PMID 36712920, 2023).
prostate carcinoma (11 papers, 2013 to 2025). A carcinoma that arises from epithelial cells of the prostate gland. "In prostate cancer cells, DLGAP5 has been proved to be poorly expressed in hypoxic environments and has predictive value for the prognosis of prostate cancer patients." (PMID 33312770, 2020). "DLGAP5 can stabilize spindle formation, leading to survival despite a microtubule challenge of docetaxel in androgen-regulated prostate cancer cell cycle systems." (PMID 32782440, 2020). "39, DLGAP5 levels alone have predictive power in prostate cancer." (PMID 30341281, 2018).